IL13 (interleukin 13)
Diseases named in the same sentence as IL13 in open-access papers (continued):
Sharing a sentence is not in itself a finding about the gene and the disease.
asthma (continued). "There is little controversy about the requirements for IL-4 in the induction of airway inflammation and AHR, while IL-13 direct causes AHR and mucus overproduction in asthma." (PMID 17480224, 2007). "In support of the interaction between IL-13 and CysLTs, leukotriene receptor antagonism with MK-571 inhibited IL-13-induced CysLT synthesis in bronchoalveolar lavage (BAL) fluid in a mouse model of asthma." (PMID 16776669, 2006). "While emphasizing the critical role of IL-13 in asthma, this study explored the relevance of IL-4 in regulation a membrane bound mucin, MUC4." (PMID 16551361, 2006). "Few reports that used microarray analyses applied to cultured human ASM cells demonstrated that IL-13 differentially regulates a number of important genes that are relevant for the pathogenesis of asthma." (PMID 15661077, 2005). "Leukotrienes, the products of lipoxygenases, are thought to be important mediators of IL-13-induced asthma phenotype." (PMID 16083514, 2005). "Several morphologic changes in the airways of patients with asthma have been attributed to the Th-2 produced cytokines such as IL-13 and IL-5." (PMID 15585067, 2004). "The increased expression of IL-4, IL-9, and IL-13 in our non-T2 children may appear paradoxical but likely reflects that children with severe asthma have elevated ILC2s even when they are non-T2 (low eosinophils)." (PMID 41601686, 2026). "In particular, exploring ALARM expression and function in type II immune conditions such as allergic disease, asthma, or other IL-4- and IL-13-driven pathologies will be important to determine whether this module also contributes to Th2-skewed inflammation." (PMID 41531734, 2026). "Dupilumab, a monoclonal antibody targeting IL-4 and IL-13 signaling via IL-4Rα inhibition, has emerged as an effective treatment for CRSwNP and asthma, offering significant reductions in nasal polyp burden, improvements in quality of life, and better asthma control." (PMID 41488423, 2026). "T2-high asthma is characterized by elevated eosinophil levels in peripheral blood and sputum; activation of Th-2 lymphocytes and innate lymphocytes (ILCs); and the release of proinflammatory cytokines such as interleukin (IL)-4, IL-5, and IL-13." (PMID 40806756, 2025). "We observed that only butyrate supplementation significantly alleviated asthma severity, characterized by reduced cell counts (total cells and eosinophils) and type 2 cytokines (IL-4, IL-13, and IL-5) in BALF, as well as total and OVA-specific IgG1/IgE levels in serum." (PMID 40473603, 2025). "However, in the presence of IL-13 activation as a model of severe asthma, MTOR signaling was required for key features of airway mucous cell metaplasia, MUC5AC staining levels, and number of eGC." (PMID 40446022, 2025). "However, while both ILC2 specific cytokines were elevated in the participants with asthma compared to healthy individuals, we detected no biological sex differences between males and females with asthma based on the levels of IL-13 detected in plasma." (PMID 40821845, 2025). "IL-5 and IL-13 are pivotal in the development of an allergen-sensitized asthma model." (PMID 39820222, 2025). "Similarly, in severe asthma, IL‐13 and IL‐17 levels are high; these cytokines induce airway epithelial cells to lose E‐cadherin and gain α‐smooth muscle actin (α‐SMA), indicating an EMT program." (PMID 40679787, 2025). "Research has indicated that altered levels of immune-related miRNAs (such as miR-146a and miR-106b) and inflammatory cytokines (including IL-5 and IL-13) in pediatric asthma may contribute to the progression of the disease." (PMID 40451928, 2025). "Estrogen can activate immune genes such as TLR7/TLR8 on the X chromosome, enhance eosinophil infiltration, and promote IL-13-mediated mucus secretion, making female asthma patients more prone to hormone-dependent acute exacerbations (e.g., during menstrual periods or perimenopause)." (PMID 41244254, 2025).
asthma (continued). "In asthma (particularly T2-high severe asthma), eosinophils are actively recruited to airway tissues in response to chemokines upregulated by IL-4 and IL-13 such as eotaxin-1 (CCL11), eotaxin-2 (CCL24), and eotaxin-3 (CCL26), which binds to CCR3 receptors on eosinophils." (PMID 40004192, 2025). "However, higher levels of sputum IL-13 have been reported in patients with asthma who demonstrated more mucus plugs on chest CT than those with fewer mucus plugs." (PMID 40978164, 2025). "The functions of specific cytokines in asthma are clear; specifically, IL-13 plays an important role in eosinophil accumulation and is considered a critical factor in IgE synthesis by B cells, differentiation of naïve T cells into Th2 effector cells, AHR, and airway inflammation." (PMID 40375219, 2025). "Notably, in the sputum of patients with severe asthma, ILC2s were identified as the predominant cellular source of type 2 cytokines, such as IL-5 and IL-13." (PMID 41409935, 2025). "The most correlated targets of the FEO‐03 network on asthma were IL‐13, IL‐4, and IL‐5." (PMID 40777200, 2025). "By identifying epithelial pathways that remain vulnerable even in the presence of IL-13 blockade, this study identifies new potential therapeutic targets for children with T2-high asthma who continue to experience viral-triggered exacerbations despite biologic therapy." (PMID 41427379, 2025). "The ATMOSPHERE trials were designed to identify whether a subset of patients would exhibit an enhanced response to tralokinumab, potentially enabling more targeted management of IL-13-driven asthma." (PMID 40732309, 2025). "The Th2-type cytokines IL-4 and IL-13 play key roles in asthma-related epithelial changes." (PMID 41303221, 2025). "In asthma, this relationship reflects converging type 2 pathways within the bronchial mucosa, driven by allergens and other environmental stimuli: local IL-4/IL-13 production induces iNOS and FeNO release, while IL-5 regulates eosinophil recruitment, maturation, and survival." (PMID 40981077, 2025). "For example, IL-13 signaling contributes to asthma through IgE-independent mechanisms." (PMID 40614216, 2025). "In particular, IL-4 is suggested to play an important role in early phase of asthma occurrence via positive loop to produce Th2 cell-related cytokines and IgE, but IL-13 is considered to relate with the late phase of asthma, such as mucous hypersecretion and airway remodeling." (PMID 40323927, 2025). "Additionally, Periostin has been associated with persistent and severe asthma, while IL-13 has been recognized as a key regulator of asthma chronicity in murine models." (PMID 40503233, 2025). "Delivering IL-13 to the airways induces asthma symptoms such as eosinophil infiltration and a vigorous response in the airway, while inhibition of IL-13 levels could attenuate these effects." (PMID 39820222, 2025). "Indeed, PF-07275315, a trispecific antibody targeting TSLP, IL-4 and IL-13 simultaneously, is being evaluated in Phase II trials for asthma and atopic dermatitis." (PMID 41294800, 2025). "The ROC curve was used to evaluate the predictive value of IL-13 for poor asthma control." (PMID 40260311, 2025). "TGF-β1 is a key mediator in the development of IL-13-mediated asthma phenotypes." (PMID 39949968, 2025). "Furthermore, serum periostin is an extracellular matrix protein released by airway epithelial cells stimulated with IL-13 that has potential as a biomarker of airway eosinophilia in patients with asthma." (PMID 41440490, 2025). "Dysregulated Th2 inflammation contributes to the primary pathological mechanism in asthma, driven by Th2 cells that secrete Th2 cytokines (interleukin (IL)-4, IL-5, and IL-13), thereby instigating specific inflammatory cascades and perpetuating an inflammatory response." (PMID 40343297, 2025). "Adding dupilumab to IL-13-treated cell cultures partially restored cilia in asthma patients, indicating that enhancing CLC function may help explain the therapy’s benefits." (PMID 41303221, 2025).
asthma (continued). "When we tested for nutrients associated with proinflammatory cytokines, FAs showed the most prominent negative associations with IL-2, IL-10, IL-13, and IL-17A, which play key roles in the inflammatory processes underlying asthma." (PMID 41256924, 2025). "This suggests that let‐7 miRNAs may play a protective role in asthma, potentially by inhibiting IL‐13." (PMID 40022441, 2025). "Increased IL-4, IL-5, IL-13, and IgE production characterize asthma T2 inflammation." (PMID 40486460, 2025). "In a HDM-induced asthma model, IMs are the primary source of IL-10, and they significantly alleviate neutrophil-dominated airway inflammation by inhibiting the expression of Th2/Th17-related inflammatory cytokines such as IL-13, IL-17, GM-CSF, and TNF-α." (PMID 40636260, 2025). "Despite the central role of Th2 cells in producing type 2 cytokines, the field has kept a keen interest in identifying other sources of IL‐4, IL‐5, IL‐9, and IL‐13, which may also be relevant for asthma pathobiology." (PMID 40016948, 2025). "IL-13 and IL-4 are involved in mucus overproduction in asthma." (PMID 41303221, 2025). "The impact of IL-13-driven inflammation, common in pediatric asthma, on airway epithelial antiviral and inflammatory responses to RV remain unclear." (PMID 41427379, 2025). "Furthermore, ITIH4 also suppressed IL-5 and IL-13 levels in the intestinal tissues of OVA-induced asthma mice (p < 0.05), suggesting a systemic immunomodulatory effect that extends beyond the lungs." (PMID 40410722, 2025). "It plays a role in the IL-4 and IL-13 signaling pathways in asthma and allergies." (PMID 40375219, 2025). "Its overexpression was associated with decreased levels of ovalbumin-specific IgE, IL-4, IL-5, and IL-13, contributing to improved asthma outcomes by limiting airway remodeling and autophagy through the downregulation of matrix metalloproteinase (MMP)-16 and autophagy related 7 (ATG7)." (PMID 40871238, 2025). "Let‐7 miRNAs act as immune modulators by inhibiting the production of IL‐13 and may be an important factor explaining the sex disparity seen in asthma." (PMID 40022441, 2025). "Consequently, targeting IL-13 is being considered as a potential therapeutic target in asthma, with several clinical trials being performed so far." (PMID 40723867, 2025). "Beyond diagnosis, periostin holds potential in guiding asthma phenotyping, helping identify patients with Th2-high inflammation who may benefit from targeted biologics (e.g., anti-IL-13 and anti-IL-4 receptor therapies)." (PMID 41374409, 2025). "Given this, we tested the hypothesis that Bdnf derived from epithelia regulates airway inflammatory responses to interleukin 13 (IL-13), a key pro-inflammatory mediator of asthma pathogenesis." (PMID 40626045, 2025). "In the present study, asthma patients with high IL-36Ra and IL-38 levels showed a deteriorating asthma status and were prone to SAEs; additionally, IL-36Ra and IL-38 were positively correlated with the agonistic IL-36 cytokines IL-6, IL-13, IL-17, and IFN-γ." (PMID 40115968, 2025). "For example, periostin and DPP-4 are being explored as potential predictors for IL-13-targeting biologics in asthma, while IL-33 and soluble IL-33R levels in sputum or serum may aid in selecting therapies that inhibit IL-33 signaling." (PMID 40004611, 2025). "Patients with T2-high asthma typically respond well to inhaled corticosteroids, which suppress the type 2 inflammatory cascade, and to biologic therapies targeting IL-4, IL-5, and IL-13." (PMID 40508095, 2025). "The present study showed that children with comorbid asthma and obesity/overweight had higher IL-6, TNF-α, and leptin, and lower 25-(OH) D3, IL-10, and IL-13 than children with asthma alone, and had lower IL-10 and higher IL-6, IL-13, and leptin than children with obesity/overweight alone." (PMID 40083433, 2025).
asthma (continued). "Given that asthma is a widespread noninfectious chronic condition marked by type II inflammation, we assessed the levels of Th2-associated cytokines (IL-4, IL-5, and IL-13) in bronchoalveolar lavage (BAL) fluid and serum IgE concentrations." (PMID 41146240, 2025). "Human and in vitro studies demonstrate that two microRNAs, specifically miR-155 and miR-221, were associated with T-helper 2 (Th2)-derived cytokine inflammation (IL-13) and cellular elements of the immunological response relevant to asthma, including eosinophils, macrophages, and mast cells." (PMID 41010514, 2025). "IL-13 pretreatment of all donor samples modeled a T2 environment but may not account for already existing differences in the donor epithelium due to their asthma endotype or other potential differences including epigenetic changes." (PMID 41427379, 2025). "In addition, we and others have observed that autophagy proteins are increased in the airway epithelium from asthma or in response to IL-13." (PMID 40446022, 2025). "In the Phase IIa trial (NCT00873860), a subgroup of moderate to severe uncontrolled asthmatics who had elevated sputum IL-13 at baseline showed trends toward meaningful enhancements in Asthma Control Questionnaire (ACQ-6) scores and FEV1 when compared with placebo." (PMID 40732309, 2025). "Let‐7 miRNAs may act as immune modulators in asthma by inhibiting the production of IL‐13, resulting in lower levels of IL‐13 in males compared to females." (PMID 40022441, 2025). "In addition, increased airway hyperreactivity, higher levels of lung lavage eosinophilia, IL-13, and IgE—all characteristic features of asthma pathogenesis—were noted in mice fed a methyl-rich diet vs. a regular diet." (PMID 41010514, 2025). "The common gene of the FEO‐03 network and asthma with the highest relevance score was IL13." (PMID 40777200, 2025). "Asthma is characterized by a Th2-mediated immune response, which plays a key role in the pathogenesis of allergic airway inflammation by secreting Th2 cytokines such as IL-33, IL-5, and IL-13." (PMID 40422811, 2025). "However, the levels of type-2 cytokines, such as IL-4 (10–25 pg/ml), IL-5 (10–16 pg/ml), and IL-13 (30–70 pg/ml), were enhanced in response to the type-2 high model compared to the type-2 low asthma model (0.5–3 pg/ml, 1–4 pg/ml, and 2–8 pg/ml, respectively)." (PMID 40512736, 2025). "While Th2-high asthma is driven by cytokines like IL-4, IL-5, and IL-13 and often responds well to corticosteroids and biologics, the pathogenesis and treatment of Th2-low, neutrophilic, or pauci-granulocytic asthma remain less defined and often exhibit steroid resistance." (PMID 41394843, 2025). "By targeting specific mediators of this inflammation, such as IgE, IL-5, IL-4, and IL-13, biologics aim to reduce severe asthma exacerbations, improve symptom control, and potentially reduce the need for systemic corticosteroids, thus mitigating their associated risks." (PMID 40486460, 2025). "These primed DCs induce polarization of type-2 T helper cells (Th2) at regional lymph nodes, and the Th2 cytokines IL-4, IL-5, and IL-13 subsequently promote asthma symptoms by inducing inflammatory cell recruitment, IgE production, excess mucus secretion, and airway smooth muscle cell contraction." (PMID 40517435, 2025). "Three further publications reported the influence of bae-EVs on DCs, with one study evaluating the miRNA cargo of EVs derived from primary normal human bronchial epithelial cells treated with IL-13 to induce an asthma-like phenotype and EVs isolated from nasal lavages of children with asthma." (PMID 40565252, 2025). "Over the past several years, it has become evident that IL-13 is a key mediator in the pathogenesis of allergic airway inflammation, and thereby it has been identified as a possible therapeutic target in the treatment of asthma." (PMID 40564060, 2025).
asthma (continued). "Efficacy was not demonstrated in the overall study population, suggesting additional mechanisms beyond IL/IL-13 pathways might predominate in some of the patients in this heterogeneous population of uncontrolled asthma." (PMID 40564060, 2025). "M2 Macrophages dominate in Th2-high asthma, driven by IL-4 and IL-13." (PMID 41394843, 2025). "Studies have demonstrated that inflammatory characteristics of asthma may be related to the release of Th2 cytokines (IL-4, IL-5, IL-13 and IL-33) mediated by the regulation of arachidonic acid metabolic pathway." (PMID 40771395, 2025). "The mechanism of Type 2 inflammatory asthma: Upon allergen exposure in the airways, dendritic cells (DCs) present processed allergens to Th2 lymphocytes, which subsequently secrete interleukin‐5 (IL‐5), IL‐4, and IL‐13." (PMID 41310922, 2025). "Epithelial barrier defects have been demonstrated in asthma, AD and chronic rhinosinusitis for genetic reasons, epithelial barrier toxic substances and immune system cells and cytokines involved in the type 2 response, mainly IL-4 and IL-13." (PMID 39962262, 2025). "Moreover, the addition of metformin to IL-33 reduced the presence of IL-13 and IL-5, thus suggesting the relationship between the long-known biguanide and alarmins in asthma." (PMID 40723867, 2025). "IL-4 and IL-13 are key upstream mediators of type 2 inflammation in asthma, and dupilumab, by blocking these cytokines, has been shown to significantly reduce the rate of severe exacerbations and rapidly improve asthma control." (PMID 41393760, 2025). "In vitro studies of epithelial and stromal cells frequently simulate T2-high immune environments with addition of the classical Th2 cytokines IL-4, IL-5, and IL-13, but fail to recapitulate many epithelial genes that are differentially expressed in T2-high asthma or nasal polyps in vivo." (PMID 38444858, 2024). "Importantly, the asthma-related cytokine IL-13, produced by Th2 and ILC2 cells, reduced barrier function as well as junctional proteins, including claudin-18, ZO-1, occludin, and E-cadherin." (PMID 39135743, 2024). "In individuals with asthma, exposure to allergens exacerbates this response, leading to heightened airway inflammation and impaired viral clearance due to increased production and secretion of IL-4, IL-5, and IL-13." (PMID 38674586, 2024). "Promising work by Wawrzyniak and others in primary human cells were able to reconstitute barrier function, damaged by IL4 and IL13 exposure, from asthmatic patients by inhibiting histone deacetylases (upregulated in asthma), resulting in junctional protein synthesis." (PMID 38529406, 2024). "Biologic therapies targeting key inflammatory pathways involved in viral-induced exacerbations, such as interleukin (IL)-4, IL-5, and IL-13 in asthma, and tumor necrosis factor-alpha (TNF-α) and IL-1 in COPD, show potential for modulating airway inflammation and reducing respiratory symptoms." (PMID 39458339, 2024). "Furthermore, IL-13+ ILC2s are increased in the peripheral blood of patients with uncontrolled asthma." (PMID 38785953, 2024). "The co-occurrence of active tuberculosis (TB) in patients with moderate to severe asthma presents unique therapeutic challenges, particularly with the advent of biologics like dupilumab, which targets the interleukin-4 (IL-4) and interleukin-13 (IL-13) pathways in asthma treatment." (PMID 39280557, 2024). "A study of the suppressive effect of thioredoxin on airway inflammation using a mouse model of asthma showed that IL-13 and exotoxin production were significantly reduced in TRX-transgenic (TRX-Tg) mice, which reduced eosinophil recruitment and decreased mucus metaplasia." (PMID 39403377, 2024). "Indeed, the expression of periostin is increased in the airways of asthma patients and can be induced by IL-13/IL-4 in vitro." (PMID 38785953, 2024). "IL‐13 and IL‐6 are extensively suggested to be significantly related to the asthma pathogenesis." (PMID 39239069, 2024).